ASMTL (acetylserotonin O-methyltransferase like)
Description:
Nucleoside triphosphate pyrophosphatase that hydrolyzes dTTP and UTP. Can also hydrolyze CTP and the modified nucleotides pseudo-UTP, 5-methyl-UTP (m(5)UTP) and 5-methyl-CTP (m(5)CTP). Has weak activity with dCTP, 8-oxo-GTP and N(4)-methyl-dCTP. May have a dual role in cell division arrest and in preventing the incorporation of modified nucleotides into cellular nucleic acids. In addition, the presence of the putative catalytic domain of S-adenosyl-L-methionine binding in the C-terminal region argues for a methyltransferase activity (Probable).
Synonyms: ASMTLX; ASMTLY; ASTML
Tractability: PROTAC: ubiquitination databases record sites on it; its protein half-life has been measured.
Gene: Protein-coding gene on chromosome X (1,403,138 to 1,453,786, reverse strand). Ensembl gene ENSG00000169093.
Subcellular location (Human Protein Atlas): Cytosol
Gene Ontology:
Molecular function: dTTP diphosphatase activity; protein binding; UTP diphosphatase activity; nucleoside triphosphate diphosphatase activity; methyltransferase activity; O-methyltransferase activity; protein dimerization activity
Cellular component: cytosol
Homologues: Orthologues: chimpanzee ASMTL (82% identical), pig ASMTL (64% identical), dog ASMTL (64% identical), macaque ASMTL (63% identical), tropical clawed frog asmtl (54% identical), zebrafish asmtl (51% identical), rat Asmtl (18% identical), Drosophila melanogaster CG9515 (14% identical), Caenorhabditis elegans dod-18 (13% identical). Paralogues in human: ASMT (24% identical).
Diseases named in the same sentence as ASMTL in open-access papers:
ASMTL is named in the same sentence as 4 diseases in open-access papers, as found by Europe PMC text mining. Sharing a sentence is not in itself a finding about the gene and the disease. The quoted sentences say what the papers report.
depression (1 paper, 2023). "Genes associated with depression or neuro-diseases were found in this study, such as ABCG1, ASMTL, CACNA1F, COX7A1, GRID2, HTR3E, and SHANK2." (PMID 37766304, 2023).
ASMTL also shares sentences with these, for which no sentence is quoted: infection (1 paper); tumor (1); viral infection (1).